ALDH1A3 (aldehyde dehydrogenase 1 family member A3)
Diseases named in the same sentence as ALDH1A3 in open-access papers (continued):
Sharing a sentence is not in itself a finding about the gene and the disease.
breast carcinoma (continued). "Knockdown of ALDH1A3 but not ALDH1A1 in breast cancer cells decreased ALDH activity, and knockdown of ALDH1A1 reduced breast cancer cell metastatic behavior and therapy resistance relative to control (p < 0.05)." (PMID 28937653, 2017). "Elucidation of the mechanisms by which ALDH1A1, ALDH1A3 and other ALDH isozymes contribute to disease progression could have potentially important implications for the management and treatment of breast cancer in the future." (PMID 28937653, 2017). "Relevant to this, Marcato and Lee's groups have demonstrated that ALDH1A3-mediated modulation of RA-target genes contributes in vivo protumorigenic properties including the transcription of the MUC4 oncogene, to MDA-MB-231 breast cancer cells." (PMID 25868979, 2015). "Interestingly, in human epidermal growth factor 2 overexpressing (HER2+) breast cancers, ALDH1A3 expression did not correlate with PLAT expression." (PMID 37753740, 2024). "In MDA‐MB‐231 cells, the decreased PAI‐2 could contribute to the increased tPA, uPA, and plasmin activity induced by ALDH1A3; however, given its absence in MDA‐MB‐436 cells, its role in ALDH1A3‐mediated plasmin activity in the breast cancer cells may be less important." (PMID 37753740, 2024). "Furthermore, in the present study, even after ALDH1A3 knockdown, there was still approximately 50% normal ALDH activity, indicating that other ALDH isozymes might be involved in the context of breast cancer." (PMID 28937653, 2017). "Furthermore, ALDH1A3 may be a potential TNBC-specific candidate gene, which providing novel treatment options for breast cancer." (PMID 27842518, 2016). "In breast cancer, mixed results have been reported regarding the specific ALDH1A isoenzyme involved in tumorigenesis and the ALDEFLUORTM assay, with some groups reporting ALDH1A1 as the main enzyme involved and others showing that ALDH1A3 is the accountable isoform." (PMID 26445849, 2016). "We evaluated the association between tumor tissue ALDH1A1/ALDH1A3 mRNA expression and triple-negative breast cancer (TNBC) prognosis in the Shanghai Breast Cancer Survival Study (SBCSS, N=463), Nashville Breast Health Study (NBHS, N=86), and Southern Community Cohort Study (SCCS, N=47)." (PMID 26462023, 2015). "Moreover, evidence has demonstrated that NANOG signalling induces enhanced ALDH1A3 activity through activation of the Notch1 and AKT pathways, which in turn stimulates DNA double-strand break repair capacity and confers radio resistance to breast cancer cell lines." (PMID 36651035, 2023). "Earlier studies indicate that it is ALDH1A3, not ALDH1A1, that contributes to ALDH activity in basal-like breast cancer cell lines, and ALDH1A3 is reported to positively associate with tumor grade, stage and metastasis." (PMID 32658903, 2020). "In a distinct study, shRNA knock-down data indicated that ALDH1A3, not ALDH1A1, correlated best with ALDH activity in breast cancer stem cells." (PMID 23484127, 2013). "Our results support previous studies, which have shown that ALDH1A3 is highly expressed in ALDHbr cells and that ALDH1A1 expression may not be directly related to proliferation and metastasis in breast cancer." (PMID 32423137, 2020). "Interestingly, when we investigated the expression of CSC-related genes in the luminal breast cancer cell line MCF7 without drug treatment, the expression of ALDH1A3, OCT4, and NANOG did not vary as a function of in vitro model." (PMID 28871147, 2017).
glioblastoma (47 papers, 2013 to 2025). The most malignant astrocytic tumor (WHO grade IV). "Selective inhibition of ALDH1A3 caused a decline in glioblastoma and colorectal cancer proliferation and invasion." (PMID 37511575, 2023). "Mesenchymal glioblastoma stem cells also demonstrate increased glycolytic activity associated with ALDH1A3 expression." (PMID 36672441, 2023). "Recent studies have placed significant emphasis on the association between ALDH1A3 and reactive oxygen species (ROS) metabolism, as well as its role in sensitizing glioblastoma cells to ferroptosis." (PMID 37947601, 2023). "Our study further supports the association of ALDH1A3 with glioblastoma stem cells and provide evidence for the regulation of ALDH1A3 activities at the level of protein turnover." (PMID 35052687, 2021). "This correlates with other studies showing that high ALDH1A3 expression is associated with more aggressive forms of breast, glioblastoma, glioma, and pancreatic cancer." (PMID 27724856, 2016). "In addition, high ALDH1A3 expression is associated with worse patient survival in prostate, glioblastoma, neuroblastoma, pancreatic, gastric, gall bladder, colon, and intrahepatic cholangiocarcinoma cancers." (PMID 36672441, 2023). "In glioblastoma (GBM), like in many other tumors, ALDH1A3 expression was linked to tumor stem cells and more specifically to cancer stem cells of GBM, with a transcriptomic signature indicated as mesenchymal." (PMID 39001459, 2024). "The similar efficiency of WP1130 was also showed in glioblastoma which resolve the ALDH1A3+ CSCs-driven chemoresistance problem." (PMID 40246814, 2025). "In glioblastomas, the interaction of ALDH1A3 with PKM2 promotes tetramer formation, leading to lactate accumulation in cancer stem cells." (PMID 39979245, 2025). "In particular, the ALDH1A3 isoform has gained significant attention due to its overexpression in various types of cancers such as breast, prostate, ovarian cancer, glioblastoma and melanoma." (PMID 40887554, 2025). "Glycolytic reprogramming-induced XRCC1 lactylation induced therapeutic resistance in ALDH1A3-overexpressing glioblastoma." (PMID 41035644, 2025). "Hypermethylation of the ALDH1A3 promoter leading to lower ALDH1A3 expression was the strongest predictor of favorable outcome in a set of patients with primary glioblastoma." (PMID 41210994, 2025). "Targeting this pathway with the ALDH1A3 inhibitor D34–919 reverses resistance, underscoring the potential of lactylation-related interventions in glioblastoma therapy." (PMID 40433363, 2025). "In glioblastoma, ALDH1A3 promotes mesenchymal phenotype of GSCs, facilitating aggressive tumour behaviour and therapy evasion." (PMID 40887554, 2025). "Mechanisms by which ALDH1A3 promotes malignant progression of glioblastoma remain elusive posing a challenge for rationalization of ALDH1A3 targeting in glioblastoma, and it is also unclear how ALDH1A3 regulates glioblastoma cells stemness." (PMID 39513909, 2024). "Our ALDH1A3 knockout results in A172 glioblastoma cells align with other studies showing that reduced ALDH activity increases sensitivity to chemotherapeutic agents like TMZ, possibly due to enhanced lipid peroxidation and impaired autophagy." (PMID 39519068, 2024). "ALDH1A3 is a marker for mesenchymal glioblastomas characterized by a greater degree of aggressiveness compared to other major subtypes." (PMID 39513909, 2024). "Our main finding is that ALDH1A3 exerts cell-state dependent impact on proliferation of glioblastoma stem cells." (PMID 39513909, 2024). "Here, we review the current knowledge about ALDH1A3, one of the 1A isoforms, in cancers with an emphasis on two of the deadliest tumors that affect humans: glioblastoma multiforme and mesothelioma." (PMID 39001459, 2024).
glioblastoma (continued). "ALDH1A3 has been shown to correlate with poor patient survival, disease progression, and recurrence in many cancers, including breast, prostate, glioblastoma, neuroblastoma, pancreatic, gastric, gall bladder, colon, and intrahepatic cholangiocarcinoma cancers." (PMID 37753740, 2024). "Congruent effects ALDH1A3 and radiation on self-renewal and proliferation provides a framework for promoting glioblastoma growth under radiation treatment." (PMID 39513909, 2024). "The results showed that ALDH1A3 expression varies considerably across heterologous GSCs derived from either newly diagnosed or recurrent glioblastoma (ndGB or recGB, respectively)." (PMID 39513909, 2024). "The cooperative effects of ALDH1A3 and radiation in boosting proliferation of differentiated progenies underscore the potential merit of ALDH1A3 inhibition as an approach for impeding glioblastoma radioresistance." (PMID 39513909, 2024). "The growth reduction of the glioblastoma stem cells followed by ALDH1A3 inhibition demonstrates the tumor-promoting effects of ALDH1A3 connected to glycolysis." (PMID 36672441, 2023). "High levels of ALDH1A3 are correlated with increased tumor grade in breast, glioblastoma, bladder, and prostate cancer." (PMID 36672441, 2023). "Evidence has shown that ALDH1A3 plays a key role in the chemotherapy resistance of glioblastoma by controlling autophagy during treatment." (PMID 36996494, 2023). "Curcumin-based fluorescent probes are presented that are able to selectively bind to aldehyde dehydrogenase 1A3 (ALDH1A3), an enzyme overexpressed in glioma stem cells and specifically identify glioblastoma cells in vitro and in vivo." (PMID 36050388, 2022). "As show in result section, we confirmed our data also in vivo on model of orthotopic transplantation of GL261 glioblastoma cells, positive at the ortholog of human ALDH1A3." (PMID 36050388, 2022). "The present study aimed to quantify these DSF effects in glioblastoma stem cells in vitro, regarding dependence on ALDH1A3 expression." (PMID 34827559, 2021). "The ALDH1A3 is a well-known characterizing gene of glioblastoma, and its role and its over expression is correlated with alterations in the glycolysis/gluconeogenesis pathway." (PMID 33478031, 2021). "The present study disclosed a strong tumoricidal effect of disulfiram/Cu2+ in primary cultures of ALDH1A3+ and ALDH1A3− glioblastoma stem cells." (PMID 34827559, 2021). "Overall, our work confirms the role of ALDH1A3 as an important target in glioblastoma and colorectal cells and propose NR6 as a promising molecule for future preclinical studies." (PMID 33478031, 2021). "The effect of NR6 on cancer cells has been analyzed in vitro using ALDH1A3-expressing human glioblastoma and colorectal cancer cells." (PMID 33478031, 2021). "To further evaluate the contribution of ALDH1A3 to the metabolism of retinoids, we modified the human glioblastoma cell line U87MG43 using the CRISPR/cas9 system to create U87MG/ALDH1A3-KO cells." (PMID 34934174, 2021). "Targeting glycolytic enzymes also presented promising results in the mesenchymal subtype of glioblastoma CSCs that overexpress ALDH1A3." (PMID 29991569, 2018). "Previous study showed that ALDH1A3 induces mesenchymal differentiation in glioblastoma." (PMID 40456663, 2025). "Similarly, in glioblastoma stem cells, ALDH1A3-driven pyruvate kinase activation promotes XRCC1 lactylation-mediated DNA repair and resistance to chemoradiotherapy." (PMID 40433363, 2025). "Moreover, studies in glioblastoma (GBM) revealed that aldehyde dehydrogenase 1A3 (ALDH1A3) interacts with pyruvate kinase M2 (PKM2), enhancing its tetramerization and thus promoting lactate production." (PMID 40843350, 2025). "Similarly, in human glioblastoma, inhibition of ALDH1A3 enzymatic activity by chemical inhibitors protected tumor cells from RSL3-induced ferroptosis by regulating ferritinophagy and intracellular iron release." (PMID 41444219, 2025).
glioblastoma (continued). "Furthermore, gene expression of four tested GSC markers (CD133, SOX11, ALDH1A3, S100A4) was markedly reduced upon REST loss compared with wild-type glioblastoma cells." (PMID 38609948, 2024). "Usage of different models with diverse genetic backgrounds and often unknown degree of stemness is one possible reason for discrepant views on the role of ALDH1A3 in glioblastoma stem cells." (PMID 39513909, 2024). "Furthermore, glioblastoma cell line U87, predominantly comprising differentiated cells, has higher levels of ALDH1A3 than any self-renewal competent GSC analyzed in this study." (PMID 39513909, 2024). "This study clarifies ALDH1A3 impacts on glioblastoma stem cells by modelling ALDH1A3 expression in an otherwise invariable genetic background with consideration of the impacts of inherent plasticity and proliferative changes associated with transitions between cell states." (PMID 39513909, 2024). "Interestingly, a modified diadzin analog synthesized to inhibit ALDH1A3 (i.e., imidazo [1,2-a] pyridine, G11), had in vivo efficacy in a glioblastoma tumor model." (PMID 36672441, 2023). "Similarly, another study reported that inhibiting ALDH1A3 in glioblastoma cells also reduced glycolytic activity, invasion, and tumor growth." (PMID 36672441, 2023). "However, the specific miRNA involved in the pathways that regulate ALDH1A3‐mediated glioblastoma (GBM) radioresistance remains to be elucidated." (PMID 37551838, 2023). "Moreover, fluorescence emission in ALDH1A3+ glioblastoma cell lines is only present in the cytosol, while the nucleus appeared unstained." (PMID 36050388, 2022). "ALDH1A3 has been emphasized as mesenchymal marker in glioblastoma cells." (PMID 33478031, 2021). "Recently, we demonstrated that the ALDH1A3 isoform was highly and uniquely expressed in mesenchymal glioma stem cells (MES GSCs) and that RNA interference-mediated suppression of ALDH1A3 expression affected the growth of MES GSCs, suggesting ALDH1A3 as a potential target for glioblastoma treatment." (PMID 34934174, 2021). "ALDH1A3 is a cancer stem cell marker in neoplasms including glioblastoma (GBM)." (PMID 32680476, 2020). "In a study on GBM, interactions between aldehyde dehydrogenase 1 family, member A3 (ALDH1A3) and PKM2 were found to enhance PKM2 tetramerization in glioblastoma stem cells (GSCs), promoting lactate accumulation." (PMID 40584966, 2025). "We believe that the development of a selective inhibitor of ALDH1A3, could lead to the investigation of a possible co-administration with the Temozolomide, the only specific drug for glioblastoma treatment, to increase the final effect of the already existing molecule, reducing the side effects." (PMID 33478031, 2021). "Hence, NR6 represents a starting point for the design and synthesis of more potent ALDH1A3 inhibitor that could be used in combination therapy with other drugs targeting glioblastoma and colorectal cancers." (PMID 33478031, 2021). "Via acting on ALDH1A3 disulfiram might specifically target mesenchymal glioblastoma stem cells." (PMID 34827559, 2021). "In glioblastoma, USP9X maintains mesenchymal identity of CSCs and promotes ionizing radiation or temozolomide resistance through deubiquitylating ALDH1A3." (PMID 40246814, 2025). "To test for a tumor-intrinsic role for ALDH1A3, we generated two independent CRISPR-Cas9 knockouts of ALDH1A3 in the cell lines with high endogenous ALDH1A3 activity: MDA-MB-468 (triple-negative breast cancer), A375 (melanoma), and LN229 (glioblastoma)." (PMID 41210994, 2025). "Among the 19 ALDH isoforms, ALDH1A3 and ALDH1A1 are the primary contributors for the high Aldefluor activity that defines ALDH+ CSCs of many cancers including, breast, melanoma, glioblastoma, lung, and prostate cancer." (PMID 39251846, 2024). "ALDH1A3, one of the enzymes that belong to the ALD1A subfamily, is also expressed at high levels in many human cancers like glioblastoma and mesothelioma." (PMID 39001459, 2024).
glioblastoma (continued). "In conclusion, our study sheds light on the complex interplay between lipid metabolism, ALDH1A3 expression, and TMZ resistance in glioblastoma." (PMID 37947601, 2023). "To evaluate the fluorescent signal of both probes in an in vivo model of orthotopic transplantation of glioblastoma cells, we decided to use the GL261, a murine transplantable high grade glioma cell line positive to ALDH1A3." (PMID 36050388, 2022). "In another highly aggressive tumor, glioblastoma (GBM), USP9X interacts with aldehyde dehydrogenase one family member A3 (ALDH1A3) and stabilizes it to promote the tumorigenic capacity of mesenchymal stem cells." (PMID 34405018, 2021). "Recently, the putative markers frequently being used to identify and/or isolate glioblastoma stem cells (GSCs) include: CD133, CD44, CD15, CD70 (CD27 L), S100A4, ALDH1A3, Nanog, OCT-4, SOX-2, and Nestin." (PMID 32429463, 2020). "ALDH1A3 in particular has been indicated as a marker that promotes GSCs and correlates with the MES phenotype and invasion in human glioblastoma." (PMID 32429463, 2020). "Mesenchymal glioblastoma SCs highly expressed the aldehyde dehydrogenase (ALDH) family, especially the enzyme ALDH1A3, which is involved in glycolysis, among other functions." (PMID 29991569, 2018). "Recent studies have found that ALDH1A3 interacted with PKM2 and facilitated PKM2 tetramerization and lactate accumulation, following by inducing the lactylation of X-ray cross complementing protein 1 (XRCC1) at K247 in glioblastoma (GBM)." (PMID 40612109, 2025). "In conclusion, DSF targets GSCs independent of ALDH1A3 expression, suggesting a therapeutic efficacy also in glioblastomas with low mesenchymal GSC populations." (PMID 34827559, 2021). "Taken together, these datasets indicate high inhibition of clonogenic survival by disulfiram in glioblastoma stem cells, independent of ALDH1A3 expression." (PMID 34827559, 2021). "We report on the structural, biochemical, and cellular characterization of NR6, a new selective ALDH1A3 inhibitor derived from an already published ALDH non-selective inhibitor with cytotoxic activity on glioblastoma and colorectal cancer cells." (PMID 33478031, 2021).